NXT1 (nuclear transport factor 2 like export factor 1)
Description:
Stimulator of protein export for NES-containing proteins. Also plays a role in the nuclear export of U1 snRNA, tRNA, and mRNA. The NXF1-NXT1 heterodimer is involved in the export of HSP70 mRNA in conjunction with ALYREF/THOC4 and THOC5.
Synonyms: P15; MTR2
Tractability: PROTAC: ubiquitination databases record sites on it; its protein half-life has been measured.
Gene: Protein-coding gene on chromosome 20 (23,350,767 to 23,354,771, forward strand). Ensembl gene ENSG00000132661.
Subcellular location: Nucleus; Nucleus speckle; Cytoplasm
Subcellular location (Human Protein Atlas): Nucleoplasm; Cytosol
Pathways (Reactome):
Metabolism of RNA: Transport of Mature mRNA derived from an Intron-Containing Transcript
Gene Ontology:
Molecular function: protein binding; small GTPase binding
Biological process: mRNA export from nucleus; poly(A)+ mRNA export from nucleus; nucleocytoplasmic transport
Cellular component: cytosol; nuclear RNA export factor complex; nucleoplasm; nucleus; cytoplasm; nuclear pore; nuclear pore central transport channel; nuclear speck
Genetic constraint (gnomAD): Loss-of-function variants: 3 observed, 10.49 expected, observed/expected ratio (o/e) 0.29, 90% interval 0.13 to 0.74. The upper end of that interval is the gene's LOEUF score, 0.74, which puts it in group 3 of 6, group 1 being the genes least tolerant of losing a copy. Missense variants: 91 observed, 186.02 expected, observed/expected ratio (o/e) 0.49, 90% interval 0.41 to 0.58. Synonymous variants: 53 observed, 68.09 expected, observed/expected ratio (o/e) 0.78, 90% interval 0.62 to 0.98.
Homologues: Orthologues: chimpanzee NXT1 (100% identical), macaque NXT1 (100% identical), mouse Nxt1 (99% identical), rabbit NXT1 (98% identical), rat Nxt1 (98% identical), guinea pig NXT1 (97% identical), pig NXT1 (95% identical), Drosophila melanogaster Nxt1 (39% identical), Caenorhabditis elegans nxt-1 (29% identical). Paralogues in human: NXT2 (74% identical), NUTF2 (23% identical).
Diseases named in the same sentence as NXT1 in open-access papers:
NXT1 is named in the same sentence as 15 diseases in open-access papers, as found by Europe PMC text mining. Sharing a sentence is not in itself a finding about the gene and the disease. The quoted sentences say what the papers report.
neuroblastoma (2 papers, 2021 to 2025). Neuroblastoma (NB) is the most common solid, extracranial childhood tumor. "A similar functional screening assay led to development of a cancer dependency map in MYCN-amplified neuroblastoma that identified a novel protein, Nuclear Transport Factor 2 Like Export Factor 1 (NXT1, p15), that is essential for mRNA nuclear export and cellular integrity." (PMID 34944778, 2021). "NXT1 has been identified as a rapidly lethal factor in other diseases, such as MYCN-amplified neuroblastoma." (PMID 41578763, 2025).
childhood cancer (1 paper, 2021). "Targeting of NXT1, like XPO1, promotes cell lethality and reinforces the importance of additional research focused on nuclear export machinery in childhood cancer." (PMID 34944778, 2021).
emphysema (1 paper, 2020). "Results showed that Nxt1 was down regulated (p < 0.05) while there was upregulation trend in Pla2g2a expression in smoker with sever emphysema patients in different level as compared to non-smoker." (PMID 32874197, 2020).
female sterility (1 paper, 2019). "Both Nxf2 and Nxt1 were previously identified in screens for piRNA-guided silencing in somatic and germline cells, and their depletion resulted in female sterility." (PMID 31219034, 2019).
influenza (1 paper, 2016). An acute viral infection of the respiratory tract, occurring in isolated cases, in epidemics, or in pandemics; it is caused by serologically different strains of viruses (influenzaviruses) designated A, B, and C, has a 3-day incubation period, and usually lasts for 3 to 10 days. "We used siRNA knockdown of NXT1 to determine the function of NXT1 in influenza replication." (PMID 27483302, 2016).
periodontitis (1 paper, 2022). An acute or chronic inflammatory process that affects the tissues that surround and support the teeth. "During the inflammatory response of periodontitis, the lymphocytes, macrophage and neutrophils are regulated by expression of multiple genes, such as ARHGAP10, ARPC1B, DOCK1, FGF2/4, TNFRSF1B, NXT1, and AHR, all of which were identified in our analysis." (PMID 35491409, 2022).
virus infection (1 paper, 2016). "The short-term, 24 h NXT1-knockdown cells were used for infection and WB analysis to avoid the effect of severe NXT1 depletion which might increase the cytopathic effect of virus infection and cause reduced detection of cellular proteins." (PMID 27483302, 2016).
infection (3 papers, 2016 to 2022). The state of being infected such as from the introduction of a foreign agent such as serum, vaccine, antigenic substance or organism. "To investigate the role of NXT1 in viral replication, we monitored intracellular localization of viral proteins and vRNA in the NXT1-knockdown/infected MDCK cells at different time points post-infection." (PMID 27483302, 2016). "Viral replication kinetics were then assessed at different time points post-infection and showed decreased rates of viral replication in both NXT1-knockdown MDCK and A549 cells." (PMID 27483302, 2016). "Since NXT1 plays a role in the nuclear export of cellular mRNA, tRNA, and U1 small nuclear RNA (snRNA), the host cells for infection, MDCK and A549, were partially knocked-down with NXT1 siRNA and showed a decrease of NXT1 expression without an effect on the cell viability." (PMID 27483302, 2016).
cancer (1 paper, 2025). A tumor composed of atypical neoplastic, often pleomorphic cells that invade other tissues. "This analysis also highlighted a few interesting context dependent SL gene pairs such as NXT1/NXT2, recently described as a synthetic lethal interaction in paediatric cancer models." (PMID 40968372, 2025).
tumor (1 paper, 2025). "Meanwhile, the anti-tumor effect of NXT1 deficiency in HCCwas exploredin vitro; however, the function of NXT1 in HCCin vivo remains unexamined and requires further investigation." (PMID 41578763, 2025). "Collectively, these findings indicate a distinct immune landscape between the NXT1high and NXT1low groups, which indirectly supports the potential impact of NXT1 on the tumor immune microenvironment in HCC." (PMID 41578763, 2025). "The mRNA and protein levels of NXT1 were notably elevated in tumor tissues compared to adjacent normal samples." (PMID 41578763, 2025). "Furthermore, the expression of NXT1 was analyzed in the TNM (Tumor, Node, and Metastasis) staging system (T1-T4), and the results showed significant differences between T1 and T2, as well as between T1 and T3, with an increasing expression level." (PMID 41578763, 2025). "Furthermore, in the GEO database, metastatic samples displayed a significant elevation in NXT1 expression compared to both the tumor and normal tissue samples." (PMID 41578763, 2025).
NXT1 also shares sentences with these, for which no sentence is quoted: colon cancers (1 paper); COVID-19 (1); hepatocellular carcinoma (1); HIV-1 infection (1); muscular dystrophy (1).